ARMC9 (armadillo repeat containing 9)
Description:
Involved in ciliogenesis. It is required for appropriate acetylation and polyglutamylation of ciliary microtubules, and regulation of cilium length. Acts as a positive regulator of hedgehog (Hh)signaling (By similarity). May participate in the trafficking and/or retention of GLI2 and GLI3 proteins at the ciliary tip (By similarity).
Synonyms: KIAA1868; FLJ12584; ARM; KU-MEL-1; JBTS30; NS21
Tractability: PROTAC: ubiquitination databases record sites on it; its protein half-life has been measured.
Gene: Protein-coding gene on chromosome 2 (231,198,546 to 231,376,848, forward strand). Ensembl gene ENSG00000135931.
Subcellular location: Cytoplasm, cytoskeleton, cilium basal body; Cell projection, cilium; Cytoplasm, cytoskeleton, microtubule organizing center, centrosome, centriole
Subcellular location (Human Protein Atlas): Flagellar centriole; Annulus; Mid piece
Gene Ontology:
Molecular function: identical protein binding; protein binding
Biological process: cilium assembly; positive regulation of smoothened signaling pathway
Cellular component: centriole; ciliary basal body; extracellular exosome; ciliary tip; cilium
Genetic constraint (gnomAD): Loss-of-function variants: 79 observed, 97.68 expected, observed/expected ratio (o/e) 0.81, 90% interval 0.67 to 0.98. The upper end of that interval is the gene's LOEUF score, 0.98, which puts it in group 4 of 6, group 1 being the genes least tolerant of losing a copy. Missense variants: 872 observed, 978.81 expected, observed/expected ratio (o/e) 0.89, 90% interval 0.84 to 0.94. Synonymous variants: 348 observed, 384.97 expected, observed/expected ratio (o/e) 0.9, 90% interval 0.83 to 0.99.
Gene-disease validity (ClinGen):
ClinGen rates the evidence that ARMC9 causes each of these diseases.
Joubert syndrome 30 (autosomal recessive): Definitive.
Homologues: Orthologues: chimpanzee ARMC9 (99% identical), macaque ARMC9 (95% identical), mouse Armc9 (86% identical), pig ARMC9 (85% identical), rat Armc9 (84% identical), dog ARMC9 (81% identical), rabbit ARMC9 (69% identical), guinea pig ARMC9 (67% identical), tropical clawed frog armc9 (58% identical), zebrafish armc9 (37% identical), Caenorhabditis elegans F59G1.4 (16% identical).
Diseases named in the same sentence as ARMC9 in open-access papers:
ARMC9 is named in the same sentence as 19 diseases in open-access papers, as found by Europe PMC text mining. Sharing a sentence is not in itself a finding about the gene and the disease. The quoted sentences say what the papers report.
Joubert syndrome (10 papers, 2019 to 2025). Joubert syndrome (JS) is characterized by congenital malformation of the brainstem and agenesis or hypoplasia of the cerebellar vermis leading to an abnormal respiratory pattern, nystagmus, hypotonia, ataxia, and delay in achieving motor milestones. "Mutations in ARMC9, which encodes a basal body protein, cause Joubert syndrome, a ciliopathy with defects in the brain, kidney, and eye." (PMID 38949024, 2024). "Building on the observation that NDUFAF2 deficiency results in ciliary abnormalities, we investigated a Joubert syndrome family with a known mutation within ARMC9." (PMID 38949024, 2024). "In our study, we identified two cases, MOL2246-1 and MOL22151-1, marking the first documented instances in Israel of Joubert syndrome associated with mutations in the ARMC9 and LAMA1 genes, respectively." (PMID 39062705, 2024). "Moreover, CCDC66 is part of a ciliary tip module that includes other MAPs such as CEP104, CSPP1, TOGARAM1 and ARMC9, which are mutated in the Joubert syndrome." (PMID 40729374, 2025). "Mutations in the canonical ARMC9 cause Joubert syndrome, a neuro-developmental ciliopathy." (PMID 40455876, 2025). "Moreover, the interactome contained components of the CCDC66-linked Joubert syndrome module, such as ARMC9, TOGARAM1, CEP104 and CSPP1, known for their roles in cilium length regulation." (PMID 40729374, 2025). "Therefore, we concluded that ARMC9-deficient cells derived from a patient with Joubert syndrome exhibit mitochondrial defects, which can be rescued by NDUFAF2 expression." (PMID 38949024, 2024). "The precise mechanisms that link genetic mutations in the ciliary transition zone, including of ARMC9, to the systemic impairments in Joubert syndrome are unknown." (PMID 38949024, 2024). "Importantly, we show that a patient with Joubert syndrome due to ARMC9 mutation had a decreased level of NDUFAF2 protein, deficient mitochondrial activity, and increased oxidative stress." (PMID 38949024, 2024). "One of the Joubert syndrome proteins, ARMC9, is located at the centriole basal body and interacts with CCDC66 and TOGARAM1 to stabilize cilia membrane." (PMID 38949024, 2024). "Among 8 probands, we identified 12 variants in 7 genes associated with ciliopathies including Joubert syndrome (KIAA0586, ARMC4, BBS1, CEP83, ARMC9, TOGARAM1, WDR5)." (PMID 38585811, 2024). "Another protein that acts at B-tubules’ + ends is LisH domain-containing protein ARMC9 (ARMC9), mutations in which cause Joubert syndrome in humans, and ciliopathy phenotypes in zebrafish." (PMID 30769894, 2019). "Here we reconstituted in vitro the individual and collective activities of the ciliary tip module proteins CEP104, CSPP1, TOGARAM1, ARMC9 and CCDC66, which interact with each other and with microtubules and, when mutated in humans, cause ciliopathies such as Joubert syndrome." (PMID 39856351, 2025). "Among the genes remaining in the short list and for which the KO model does not exist, Armc9 gene mutations have been described in human Joubert syndrome, but the variety of phenotypes does not include a phenotype related to reproduction." (PMID 33198087, 2020).
ciliopathy (7 papers, 2019 to 2025). A genetic disorder of the cellular cilia or the cilia anchoring structures, the basal bodies, or of ciliary function. "Additionally, the human Armc9 (armadillo repeat containing 9) protein has recently been associated with primary cilia function and ciliopathies." (PMID 35155449, 2021). "Further, polyglutamylation was described to affect the JS-related ARMC9/TOGARAM1 protein complex, indicating that this PTM is closely related to this ciliopathy." (PMID 36674791, 2023).
Vertigo (2 papers, 2021 to 2022). An abnormal sensation of spinning while the body is actually stationary. "Variants in OTOG and otogelin like (OTOGL), otopetrin 1 (OTOP1), tectorin α (TECTA), zinc finger protein 91 (ZNF91), and armadillo repeat containing 9 (ARMC9) were associated with vertigo in a recent genome-wide meta-analysis." (PMID 35741759, 2022).
Cerebellar hypoplasia (1 paper, 2022). Cerebellar hypoplasia is a descriptive term implying a cerebellum with a reduced volume, but a normal shape and is stable over time. "Recently, a large exome sequencing study of children and adults with DWM and cerebellar hypoplasia expanded the list of genes associated with DWM to include TUBA1A, BRAF, SETD2, FOXP1, PUS3, ARMC9, and PIBF1." (PMID 35202430, 2022).
gastric cancer (1 paper, 2021). A primary or metastatic malignant neoplasm involving the stomach.
ptosis (1 paper, 2022). The drooping of the upper eyelid. "In their study, patients with ARMC9 biallelic mutations showed typical JS manifestations, such as “molar tooth sign,” and also some degree of phenotypic variability, mainly in the presence of apnea, ptosis, and polydactyly." (PMID 35186037, 2022).
tumor (1 paper, 2020). "The GSE54129 GC dataset and LASSO regression model (tumor vs. normal) were employed, and 6 significant differentially expressed genes (LAMP5, CEBPB, ARMC9, PAOX, VMP1, POC1A) were identified." (PMID 33052878, 2020).
ARMC9 also shares sentences with these, for which no sentence is quoted: autoimmune uveitis (1 paper); cleft palate (1); coloboma (1); developmental delay (1); Encephalocele (1); holoprosencephaly (1); Intellectual disability (1); neurodevelopmental disorder (1); retinal diseases (1); Retinal dystrophy (1); vitiligo (1); Vogt-Koyanagi-Harada disease (1).